WFS1 (wolframin ER transmembrane glycoprotein)
Diseases named in the same sentence as WFS1 in open-access papers (continued):
Sharing a sentence is not in itself a finding about the gene and the disease.
Wolfram syndrome (continued). "Similarly, patients with Wolfram syndrome (OMIM # 222300) frequently exhibit psychiatric symptoms due to biallelic WFS1 variants." (PMID 37895270, 2023). "However, there is phenotypic variation in syndromic monogenic diseases, as also suggested by the individual with two WFS1 variants and partial phenotype of Wolfram syndrome including diabetes mellitus and opticus atrophy." (PMID 36418577, 2023). "The WFS1 gene is mutated in Wolfram syndrome, characterized by diabetes mellitus and optic atrophy." (PMID 37440664, 2023). "Together, WFS1 c.1672C>T, p.R558C variant was enriched in the Ashkenazi Jewish population, especially those originated from Romania, and the variant led to mild or less severe phenotypes of Wolfram syndrome." (PMID 36134655, 2022). "Mutations in WFS1 are responsible for Wolfram syndrome, a recessive inherited disease." (PMID 36208030, 2022). "Wolfram syndrome is caused by recessive pathogenic variants in the Wolfram syndrome 1 (WFS1) gene." (PMID 36613674, 2022). "Wolfram Syndrome (WS) is a fatal human inherited disease with symptoms of diabetes, vision decreasing, and neurodegeneration caused by mutations in the endoplasmic reticulum (ER)-resident protein WFS1." (PMID 36527091, 2022). "β-like cells differentiated from iPSCs derived from Wolfram syndrome patients showed decreased insulin content and increased activity of molecules related to endoplasmic reticulum (ER) stress, indicating that β cell failure is caused by WFS1 deficiency." (PMID 33751396, 2022). "Although WFS1 is the responsible gene for the rare Wolfram syndrome, some of its variants may contribute to the common T2DM development." (PMID 36613674, 2022). "This hypothesis is consistent with the observation that clinically, patients carrying the homozygous WFS1 c.1672 C>T, p.R558C variant have mild or less severe phenotypes of Wolfram syndrome." (PMID 36134655, 2022). "Pathogenic variants in the WFS1 gene are the main causes of Wolfram syndrome." (PMID 35399956, 2022). "Thus, the WFS1 c.1672C>T, p.R558C variant causes a mild form of Wolfram syndrome phenotypes, which can be remitted with a combination treatment of chemical chaperones." (PMID 36134655, 2022). "Also, to the best of our knowledge, there are no transgenic animals with phenotypes and variants corresponding to the pathogenic WFS1 variants found in patients with Wolfram syndrome." (PMID 36134655, 2022). "Approximately 200 WFS1 pathogenic variants have been identified in Wolfram syndrome." (PMID 36613674, 2022). "WFS1 autosomal recessive deletion mutation can lead to Wolfram syndrome." (PMID 36445321, 2022). "Although homozygous or compound heterozygous mutations in the WFS1 gene are the main causes of Wolfram syndrome, it is less known whether common variants in WFS1 could confer a higher risk of type 2 diabetes." (PMID 36294752, 2022). "Pathogenic variants of the WFS1 gene (OMIM:606210) may cause Wolfram syndrome, Wolfram-like syndrome, or autosomal dominant non-syndromic DFNA6/14/38." (PMID 35884828, 2022). "We systematically identified all potentially relevant articles from PubMed and Web of Science, Search terms about “Wolfram syndrome” and “WFS1” and “CISD2” and “gene mutation sites”, were used in various combinations and permutations across the databases.There were a total of 26 papers." (PMID 34404380, 2021). "Beta-like cells differentiated from iPSCs of Wolfram syndrome patients showed decreased insulin content and increased activity of molecules related to endoplasmic reticulum stress, suggesting that beta cell failure is caused by WFS1 deficiency." (PMID 34680532, 2021). "Furthermore, our results propose a potential molecular mechanism underlying the diabetes association with Wolfram syndrome induced by WFS1 pathogenic mutations." (PMID 34848728, 2021).
Wolfram syndrome (continued). "Patient SC-β cells experienced higher levels of ER and mitochondrial stress than corrected cells, and displayed higher levels of expression for apoptosis markers, as generally observed in cases of WFS1 gene deficiency and consistent with a previous Wolfram Syndrome iPSC study." (PMID 33996792, 2021). "As GLP1RA may be considered as a potential therapy for wolfram syndrome treatment, analysis of association between WFS1 gene polymorphism and GLP1RA efficacy becomes reasonable." (PMID 32961860, 2020). "Also, the reduced level of WFS1 is linked with a genetic condition leading to Wolfram syndrome which causes severe depression, psychosis, or organic brain syndrome, as well as impulsive verbal and physical aggression." (PMID 32231775, 2019). "Mutations in WFS1 are responsible for the majority of Wolfram syndrome cases." (PMID 31796109, 2019). "Mutations in WFS1 are known to cause the Wolfram syndrome (WFS; OMIM 222300), an autosomal recessive neurod-egenerative disorder that is clinically defined by diabetes insipidus, young-onset non-immune insulin-dependent diabetes mellitus, optic atrophy, and deafness." (PMID 29988211, 2017). "Furthermore, patients heterozygous for the H313Y mutation in WFS1 exceptionally exhibit Wolfram syndrome in an autosomal dominant manner." (PMID 28208663, 2017). "WFS1 is localized on the ER membrane, and ER stress enhances its expression, which suggests mutations in WFS1 may render cells vulnerable to ER stress that leads to cell death and onset of Wolfram syndrome." (PMID 28208663, 2017). "Wolframin (WFS1) is a transmembrane ER resident protein encoded by the WFS1 gene that in a mutant form causes Wolfram syndrome 1 (WS1), an autosomal recessive degenerative disease characterized by insulin-dependent diabetes mellitus, optic atrophy, deafness and various neurological symptoms." (PMID 28540288, 2017). "Wolfram syndrome (WS) is an autosomal recessive disorder caused by mutations in WFS1 gene." (PMID 27468121, 2017). "They studied the gene WFS1, which is mutated in a disorder called Wolfram syndrome." (PMID 26371507, 2015). "The Wfs1 protein has long been implicated in the generation of its titular disease, Wolfram Syndrome, which is an inherited autosomal recessive neurodegenerative disorder associated with visual/auditory sensory atrophy and also significant diabetic pathophysiologies." (PMID 26635614, 2015). "Although genome-wide association studies (GWAS) have demonstrated that common depression is likely to result from alterations in a very large number of genes of small effect, studies of Wolfram syndrome have identified Wfs1 as a clear example of a gene that can cause MDD in humans." (PMID 26371510, 2015). "Both copies of WFS1 must be mutated to cause Wolfram syndrome." (PMID 26371507, 2015). "Wolfram Syndrome has been linked to mutations in both WFS1 and CISD2 (Miner1)." (PMID 23703906, 2013). "Furthermore, the finding of unexplained thiamine deficiency in a patient with Wolfram syndrome suggests a potential link between WFS1 biology and thiamine metabolism that has implications for the clinical management of Wolfram syndrome patients." (PMID 22226368, 2012). "So far, about 110 mutations in WFS1 are believed to cause the Wolfram syndrome." (PMID 20069065, 2010). "Our report of two novel WFS1 mutations expands the molecular spectrum of Wolfram syndrome." (PMID 18660851, 2008). "The classic phenotype associated with WFS1 mutations is Wolfram syndrome (DIDMOAD), a rare autosomal recessive neurodegenerative disorder characterized by Diabetes Insipidus, Diabetes Mellitus, Optic Atrophy, and Deafness." (PMID 41614934, 2026). "Wolfram syndrome (DIDMOAD), resulting from WFS1 mutations, typically manifests with diabetes mellitus, optic atrophy, and SNHL, with some cases exhibiting RP-like retinal degeneration." (PMID 41555919, 2025).
Wolfram syndrome (continued). "WFS1-associated deafness is also linked with diabetes insipidus, diabetes mellitus, and retinal ganglion cell–related optic nerve atrophy in people as part of the clinical symptoms of Wolfram syndrome and DIDMOAD (diabetes insipidus, diabetes mellitus, optic atrophy, and deafness)." (PMID 39570676, 2025). "For example, Wolfram syndrome (DIDMOAD) is caused by mutations in WFS1, a gene encoding an endoplasmic reticulum (ER) protein rather than a mitochondrial protein." (PMID 40332750, 2025). "WFS1 (Wolframin) is known as an ER protein containing nine predicted transmembrane domains (Fig. 5a56) and is linked to the autosomal recessive neurodegenerative disease Wolfram syndrome (WS), characterized by early-onset diabetes, optic atrophy, and hearing loss." (PMID 40097443, 2025). "Therefore, considering the unmet need of treatment for this orphan disease, we set out to test the therapeutic potential of GLP-1R agonists not only in WFS1-deficient mice, but also in human WFS1-deficient beta cells and neurons, and in a humanised mouse model of Wolfram syndrome." (PMID 36995380, 2023). "Considering that the Wolfram syndrome iPSCs used here had different WFS1 mutations from the ones utilised in the previous study, the ER stress-mediated mitochondrial failure in iPSC-derived beta cells may also depend on specific WFS1 pathogenic variants." (PMID 36995380, 2023). "The main causal gene of Wolfram syndrome is WFS1, at present, we have collected clinical phenotypes, but it is not clear whether these mutants are directly involved in the development of the disease and the relationship between these mutations and the phenotypes." (PMID 37974252, 2023). "WFS1-deficient cells are vulnerable to ER stress, which promotes VegfA expression, which may lead to hypervascularization and macrophage infiltration in the Wolfram syndrome model mice islets." (PMID 35399956, 2022). "Wolfram Syndrome (WFS) is a rare, neurodegenerative syndrome caused by a mutationin the WFS1 or WFS2 gene." (PMID 36620710, 2022). "Moreover, we describe new treatment methods targeting protein folding and ER stress pathways with a particular focus on pivotal studies of Wolfram syndrome, a monogenic form of syndromic diabetes caused by pathogenic variants in the WFS1 gene, which also leads to ER dysfunction." (PMID 36613674, 2022). "The p.R558C variant showed less thermal stability than wild-type WFS1, suggesting an altered folding state, but more stability compared with the known autosomal recessive variant p.P885L, which is pathogenic and is associated with a typical form of Wolfram syndrome." (PMID 36134655, 2022). "WFS1 on chromosome 4 is the causative gene of Wolfram Syndrome type 1 (WFS1), and the loss-of-function mutations of WFS1 have been identified in most of patients with WFS." (PMID 31391115, 2019). "Wolfram syndrome (WFS) (OMIM 222300) is caused by recessive mutations mainly in the WFS1 gene on chromosome 4p16.1." (PMID 28856555, 2017). "A number of loss-of-function mutations of the Wolfram syndrome 1 gene (WFS1) have been described in patients with WFS." (PMID 25211237, 2014). "Wolfram syndrome (WFS), a monogenic diabetes, is caused by mutations in the WFS1 gene, another important ER gene." (PMID 21050479, 2010). "Homozygous or compound heterozygous mutations in WFS1 may lead to the autosomal recessive inherited Wolfram syndrome, presenting a variety of phenotypes, including diabetes insipidus, diabetes mellitus, optic atrophy, and deafness, referred to as DIDMOAD (OMIM:#222300)." (PMID 17517145, 2007). "Wolfram syndrome is considered a prototype ER disorder, as both WFS1 and CISD2 proteins localize to the ER and are crucial for maintaining ER homeostasis." (PMID 41234236, 2025). "Wolfram syndrome (WFS) is a genetic disorder mainly caused by pathogenic variants in the WFS1 gene." (PMID 41245872, 2025).
Wolfram syndrome (continued). "Wolfram Syndrome (WFS) is a rare, neurodegenerative disorder caused by mutations in the WFS1 or CISD2 genes, leading to severe multi-organ dysfunction, including diabetes, optic atrophy, and hearing loss." (PMID 41235102, 2025). "The pathophysiological mechanism of DM in Wolfram syndrome involves the expression of the WFS1 gene in pancreatic beta cells." (PMID 39064493, 2024). "The WFS1 gene was first identified in Wolfram Syndrome 1 (WS1), a rare autosomal recessive genetic disorder characterized by severe and progressive neurodegenerative changes." (PMID 39595565, 2024). "There are three known types of Wolfram syndromes: WFS1 (OMIM #222300), WFS2 (OMIM #604928), and the mitochondrial form (OMIM #598500)." (PMID 39064493, 2024). "Another variant leading to a premature stop codon at the same position, WFS1 c.1944G>A, p.(Trp648*), has been reported as compound heterozygous (confirmed in trans) with WFS1 p.(Gly695Val) in three affected siblings with Wolfram syndrome." (PMID 39064493, 2024). "Cluster 1 (green) is primarily related to the clinical manifestations and pathological mechanisms of Wolfram syndrome, such as deafness, diabetes, and the WFS1 gene." (PMID 39835089, 2024). "We included in this panel 18 genes involved in different diseases from our consultation, among them the WFS1 (NM_006005.3) gene responsible of Wolfram syndrome." (PMID 37752530, 2023). "According to previous research, WFS1 (Wolfram syndrome 1) is involved in the synthesis and release of insulin, as well as the preservation of the pancreatic β cell mass." (PMID 36725880, 2023). "Genetic rescue by WFS1 restoration or chemical rescue by drugs modulating mitochondrial function improves the bioenergetics and viability of Wolfram syndrome patient neurons, thus providing insights for therapeutic intervention." (PMID 37163979, 2023). "In patients with Wolfram syndrome, because of the variation of WFS1, ATF6 is hyperactivated, leading to dysregulated ATF6 signaling pathway." (PMID 37185285, 2023). "One of the UPR components is WFS1 (Wolfram syndrome 1), which plays important roles in ER homeostasis and pancreatic islets glucose-stimulated insulin secretion (GSIS)." (PMID 36725880, 2023). "More than 200 different variations in the WFS1 gene have been described in Wolfram syndrome patients." (PMID 37440664, 2023). "WFS1 gene responsible for the most cases of Wolfram syndrome, was identified in 1998, maps to chromosome 4p16 and contains 8 exons (33.4 kb of genomic DNA)." (PMID 37752530, 2023). "Exenatide hence improves mitochondrial function, reduces oxidative stress and protects WFS1-deficient iPSC-derived neurons from apoptosis, supporting the therapeutic potential of GLP-1R agonists to prevent cerebellar neurodegeneration in Wolfram syndrome." (PMID 36995380, 2023). "Wolfram syndrome (WFS; DIDMOAD syndrome, OMIM#222300) is a rare (1:770,000) autosomal recessively inherited disease with the presence of pathogenic variants in the WFS1 gene, in which the life expectancy of patients is approximately 30–40 years." (PMID 36982670, 2023). "These Wfs1-KO INS-1 cells possess the characteristics of pancreatic β-cells in Wolfram syndrome: thapsigargin intolerance and mitochondrial dysfunction." (PMID 35399956, 2022). "Several Wfs1-knockout rodents were developed as disease models of Wolfram syndrome, which generated insight into the etiology and provided opportunities to test therapeutic agents." (PMID 36134655, 2022). "Our findings reveal islet-localized inflammation in Wolfram syndrome models and suggest that WFS1 functions to regulate sterile inflammation in pancreatic β-cells." (PMID 35399956, 2022). "Moreover, carriers of the WFS1 pathogenic variants can present with features unique to the Wolfram syndrome, such as congenital cataract, non-syndromic sensorineural deafness, or psychotic disorder, and these characteristics could be helpful in leading to a clinical suspicion." (PMID 36294752, 2022).
Wolfram syndrome (continued). "Mutations in the WFS1 gene are predominantly responsible for nonsyndromic hearing loss (DFNA6), Wolfram syndrome and Wolfram-like syndrome 11,12." (PMID 36564540, 2022). "There are also known WFS1-related disorders characterized by developing only one or few symptoms seen in Wolfram syndrome." (PMID 36613674, 2022). "Two types of this genetic disorder have been identified, Wolfram syndrome 1 (WFS1) and Wolfram syndrome 2 (WFS2)." (PMID 34948153, 2021). "For example, different substitutions at amino acid 678 of WFS1 resulted in three distinct phenotypes: sensorineural HL, Wolfram syndrome, and optic atrophy and diabetes." (PMID 34258273, 2021). "Among these 26 papers, five patients had wolfram syndrome caused by mutations in the CISD2 gene, while the rest had disease caused by mutations at different nucleotide sites in exons 4, 5 and 8 of the WFS1 gene." (PMID 34404380, 2021). "In the context of Wolfram syndrome, sodium valproate was shown to increase WFS1 mRNA expression in neuronal cells by activating its promoter." (PMID 34992533, 2021). "Wolfram syndrome (WS), also known as a DIDMOAD (diabetes insipidus, early-onset diabetes mellitus, optic nerve atrophy and deafness) is a rare autosomal disorder caused by mutations in the Wolframin1 (WFS1) gene." (PMID 34831417, 2021). "All papers are case reports on single nucleotide polymorphisms on the WFS1 and CISD2 genes in wolfram syndrome." (PMID 34404380, 2021). "Another gene involved in dominant ION is WFS1, the gene responsible for Wolfram syndrome, a recessive condition." (PMID 33841295, 2021). "Wolfram syndrome (diabetes insipidus, diabetes mellitus, optic atrophy, DIDMOAD) caused by mutation in the Wolframin gene (WFS1), is an autosomal recessive disorder." (PMID 32168890, 2020). "In this review, we attempt to summarize our current understanding of the Wolfram syndrome-related structural and functional brain alterations and to provide insights from new neuroimaging and WFS1 expression analyses across age and cell types." (PMID 31796109, 2019). "Recessive mutations in WFS1 and WFS2 lead to Wolfram syndrome 1 and 2, respectively, two autosomal recessive disorders with young-onset diabetes, optic nerve atrophy, and deafness." (PMID 28951826, 2017). "Glucose levels were normal in these mice as assessed by urinalysis in non-fasting conditions (data not shown), indicating that the pancreatic β cells responsible for metabolic phenotype of Wolfram syndrome were spared in the Wfs1/CKO mice." (PMID 26371510, 2015). "Wfs1 knockout mice accurately model many aspects of Wolfram syndrome, including type 1 diabetes, retinal degeneration, and impaired behavioral responses to stress." (PMID 26371510, 2015). "Previous studies have demonstrated that both patients with Wolfram syndrome and Wfs1 knockout mice display altered stress responses, including elevated levels of serum corticosterone upon exposure to stress." (PMID 26371510, 2015). "Studies of Wfs1 knockout mice have shown that they replicate central and peripheral features of Wolfram syndrome and that they display impaired behavioral adaptation to stress." (PMID 26371510, 2015). "Wolfram syndrome, also known as DIDMOAD (diabetes insipidus, diabetes mellitus, optic atrophy, and deafness), is an autosomal recessive disorder caused by more than 100 mutations in the WFS1 gene, which was identified by positional cloning in 1998." (PMID 24588001, 2014). "Here we review and discuss the pathophysiological mechanisms that we believe responsible for the perinatal onset of Wolfram syndrome as these data strongly suggest a role for WFS1 gene in foetal and neonatal neurodevelopment." (PMID 25255707, 2014). "Here we review the pathophysiological mechanisms possibly responsible for the perinatal onset of Wolfram syndrome according to the recent published evidence of WFS1 role in fetal and neonatal neurodevelopment." (PMID 25255707, 2014).